CAV3 (caveolin 3)
Diseases named in the same sentence as CAV3 in open-access papers (continued):
Sharing a sentence is not in itself a finding about the gene and the disease.
long QT syndrome 9 (6 papers, 2009 to 2024). Any long QT syndrome in which the cause of the disease is a mutation in the CAV3 gene. "For example, mutations in the CAV-3 gene promote ventricular arrhythmogenesis in long QT syndrome 9 by a combined decrease in the loss of the inward rectifier current (IK1) and gain of the late sodium current (INa-L)." (PMID 35329921, 2022). "In addition, mutations in caveolin-3 are associated with long-QT congenital syndrome." (PMID 35514336, 2022). "It has been reported that mutations in Cav3 lead to dysfunction of Nav1.5 ion channels observed in inherited arrhythmias such as long QT Syndrome 9 (LQT9)." (PMID 33228026, 2020). "More recently, four novel CAV3 mutations have been identified in patients affected by congenital long-QT syndrome (LQTS) in the absence of signs of primary cardiomyopathy, suggesting a possible role for Cav-3 in the regulation of cardiac ion channels." (PMID 20436850, 2009). "In our studies using native human ventricular tissue, Kir2.x co-localizes with caveolin-3 and significance of the association between Kir2.x and caveolin-3 is emphasized in relation to mutations in the gene which encodes caveolin-3, CAV3, associated with Long QT Syndrome 9 (LQT9)." (PMID 30473666, 2018).
rippling muscle disease (6 papers, 2007 to 2019). A benign myopathy with symptoms and signs of muscular hyperexcitability. "Rippling muscle disease is caused by mutations in the gene encoding caveolin-3 (CAV3), the muscle-specific isoform of the scaffolding protein caveolin, a protein involved in the formation of caveolae." (PMID 21294223, 2011). "Defects in Cav3 are the cause of some neuromuscular diseases such as limb-girdle muscular dystrophy type 1C (LGMD1C) and rippling muscle disease (RMD)." (PMID 22165895, 2011). "The muscle weakness of our patients resembled the pattern seen in limb girdle muscular dystrophy type 1C (LGMD1C) and rippling muscle disease (RMD), which are caused by dominant-negative mutations in CAV3." (PMID 20300641, 2010).
atherosclerosis (5 papers, 2015 to 2022). A disease characterized by the build-up of fatty material and calcium deposition in the arterial wall resulting in partial or complete occlusion of the arterial lumen. "A better understanding of the factors regulating caveolin-3 expression and function in this cell type will permit the development of a better comprehension of the factors regulating SM function in atherosclerosis and restenosis." (PMID 26664898, 2015). "CAV3 (caveolin-3) promotes vascular smooth muscle contraction and prevents atherosclerosis." (PMID 35576023, 2022). "Our findings demonstrate that caveolin-3 is a key protein that may be downregulated during atherosclerosis development or restenosis to promote vSMC dedifferentiation." (PMID 26664898, 2015). "Our data suggest that caveolin-3 may also be an important player in the regulation of SM cell function in vivo and that caveolin-3 may also play a key role in the development of atherosclerosis." (PMID 26664898, 2015).
atrial fibrillation (5 papers, 2012 to 2025). A disorder characterized by an electrocardiographic finding of a supraventricular arrhythmia characterized by the replacement of consistent P waves by rapid oscillations or fibrillatory waves that vary in size, shape and timing and are accompanied by an irregular ventricular response. "A small study in atrial fibrillation suggested associations between serum Cav-3 and atrial/clinical remodeling, but its diagnostic or prognostic value in chronic HF—and its relationship to natriuretic peptides and echocardiographic indices—remains undefined." (PMID 41143172, 2025). "Furthermore, if there is abnormally high ICa-T (e.g., overstimulation of the Cav3 channels by the sympathetic nervous system) in the cardiac pacemaking tissues and the conduction system, there could be tachycardia or atrial fibrillation or ectopic ventricular contraction." (PMID 22808078, 2012).
diabetic cardiomyopathy (5 papers, 2016 to 2024). Diabetic cardiomyopathy is a disorder of the heart muscle in people with diabetes. "Mutations in the gene encoding caveolin-3 have been linked to several cardiac diseases such as long QT syndrome, myocardial hypertrophy, and diabetic cardiomyopathy." (PMID 35872997, 2022). "Thus, any alteration of Cav-3 expression in diabetic condition may be implicated in the pathogenesis of diabetic cardiomyopathy and myocardial I/R injury." (PMID 27733157, 2016). "This indicates that enhancing Cav-3 expression is beneficial to attenuate diabetic cardiomyopathy and myocardial I/R injury." (PMID 27733157, 2016). "NAC treatment-induced restoration of Cav-3 expression attenuated diabetic cardiomyopathy and myocardial I/R injury in in vivo studies, and reduced HG and H/R induced cell injury in in vitro studies." (PMID 27733157, 2016). "Treatment with antioxidant NAC for 4 weeks attenuates diabetic cardiomyopathy and reduces myocardial I/R injury, possibly through improving Cav-3/eNOS/NO signaling." (PMID 27733157, 2016). "Ca2+ disturbances due to reduced caveolin-3 also contribute to diabetic cardiomyopathy." (PMID 32257548, 2020). "The data suggested that inhibition of excessive oxidative stress by NAC could restore Cav-3 expression and improve eNOS/NO signaling, which ultimately attenuate diabetic cardiomyopathy and myocardial I/R injury in diabetic rats." (PMID 32347295, 2020). "Therefore, it is expected that changes in the expression of caveolin-3 in any region in the heart may contribute to the pathogenesis of diabetic cardiomyopathy." (PMID 35872997, 2022).
glioma (5 papers, 2013 to 2025). A benign or malignant brain and spinal cord tumor that arises from glial cells (astrocytes, oligodendrocytes, ependymal cells). "Inhibits Cav3 (T-type calcium channel essential for external calcium entry in glioma cells), hampers a glioma cell ability to repair double-strand DNA breaks and causes cancer cell cycle arrest and apoptosis." (PMID 30271342, 2018). "Cav3, as a T-type calcium channel in synaptic plasticity, can be utilized in inhibiting glioma development through disconnecting nerve cell and OPC-like glioma cell interaction." (PMID 41018101, 2025). "The main types of Ca2+ channels described in the literature and expressed by gliomas are voltage-dependent channels (Cav1 = Type L; Cav2 = Type P/Q, R, N; Cav3 = Type T) and purinergic receptors." (PMID 31531023, 2019). "In glioma cells and pulmonary artery smooth muscle cells, the 5-HT2A receptor co-immunoprecipitates with cav-1, and in cardiomyocytes with cav-3." (PMID 28555112, 2017). "Indeed, studies showed that Cav3 (T-type) calcium channels regulate proliferation, for example, of BC3H1 cells, vascular smooth muscle (VSM) cells, and glioma, neuroblastoma, and neuroblastoma × glioma hybrid cells." (PMID 25937960, 2013).
Ventricular arrhythmia (5 papers, 2018 to 2025). "For instance, Cav-3 mutations have been shown to diminish inward rectifier potassium currents, while enhancing late sodium currents, predisposing the heart to ventricular arrhythmias." (PMID 40358155, 2025). "Additionally, we will discuss the downstream effects of Cav3 mutations on cardiac excitability as a cause for ventricular arrhythmias in inherited arrhythmia syndromes." (PMID 30473666, 2018). "Secondly, cardiac-targeted PIASy silencing mediated Cav-3 deSUMOylation and prevented I/R-induced Nav1.5 downregulation and ventricular arrhythmias." (PMID 36229865, 2022). "Cardiac-targeted PIASy silencing mediated Cav-3 deSUMOylation and partially prevented I/R-induced Nav1.5 downregulation in the plasma membrane of cardiomyocytes, and subsequent ventricular arrhythmias in rats." (PMID 36229865, 2022). "We identified novel links between PIASy-related Cav-3 SUMOylation and Nav1.5 translocation and stability, and determined a new mechanism underpinning I/R-induced Nav1.5 downregulation and fatal ventricular arrhythmias." (PMID 36229865, 2022). "Additionally, overexpression of Cav-3 can disrupt diastolic Ca2+ transients, leading to aberrant L-type Ca2+ channel activity and further exacerbating the propensity for ventricular arrhythmias." (PMID 40358155, 2025). "Caveolin-3 overexpression could lead to reduced diastolic spontaneous Ca2+ waves, thus leading to the abnormal L-Type calcium channel current-induced ventricular arrhythmias." (PMID 35329921, 2022). "I/R-induced cardiac PIASy activation increased Cav-3 SUMOylation by SUMO2/3 and dysregulated Nav1.5-related ventricular arrhythmias." (PMID 36229865, 2022). "I/R-induced activation of cardiac PIASy could increase SUMOylation of caveolin-3 (Cav-3) by SUMO2/3, leading to ventricular arrhythmias." (PMID 38033852, 2023). "Caveolin-3 overexpression could lead to the reduced diastolic spontaneous Ca2+ waves by inhibiting the hyperphosphorylation of ryanodine receptor-2 (RyR2) at Ser2814, thus leading to the abnormal LTCC current-induced ventricular arrhythmias." (PMID 35329921, 2022).
Obesity (4 papers, 2020 to 2025). Accumulation of substantial excess body fat. "Other predisposing factors include dehydration, hot environment, genetic mutations (e.g., Caveolin-3), underlying myopathy, drugs such as terbinafine and statin, obesity, and tobacco use." (PMID 32983728, 2020). "While our study was not powered for formal reclassification or net-benefit testing, these prospective analyses are planned and will clarify where Cav-3 is most effective (e.g., in populations where peptide interpretation is confounded by obesity, CKD, or AF)." (PMID 41143172, 2025). "Recent evidence indicates that caveolin-3 plays a significant role in adipose tissue and is related to obesity development." (PMID 35329921, 2022). "Dedicated analyses in obesity, CKD, and AF cohorts are warranted to test whether Cav-3 is less susceptible to peptide confounding." (PMID 41143172, 2025). "Potential resilience to common confounders: Given that NT-proBNP is depressed in obesity and altered by CKD/AF, a structurally anchored marker like Cav-3 could retain signal where peptides are noisier—an inference that warrants direct testing in enriched obese/CKD/AF subgroups." (PMID 41143172, 2025).
type 2 diabetes (4 papers, 2011 to 2025). "Moreover, overexpression of Cav-3 in liver improves insulin sensitivity, insulin receptor signaling and glucose metabolism with increased glycogen synthesis in KKAy mice with type 2 diabetes." (PMID 40012041, 2025). "It has been shown that mice with genetic ablation of Cav-3 exhibit impaired insulin signaling, abnormal glucose and lipid metabolism, adiposity, and insulin resistance with ligand-induced insulin receptor instability in skeletal muscle, which has similar features to type 2 diabetes." (PMID 40012041, 2025). "Additionally, we focus largely on type 2 diabetes induced DCM and whether and how CAV3 in type 1 diabetes associated heart injury needs further examination." (PMID 38671439, 2024). "We monitored total FAT/CD36 and caveolin 3 expression in Control derived from four different healthy subjects (1 to 4) and in OBT2D derived from three obese type 2 diabetic patients (1 to 3) cells before fractionation." (PMID 22194967, 2011).
dilated cardiomyopathy (3 papers, 2013 to 2018). Cardiomyopathy which is characterized by dilation and contractile dysfunction of the left and right ventricles. "Loss of caveolin-1 or caveolin-3 in the heart induces hypertrophy that leads to dilated cardiomyopathy." (PMID 23585895, 2013). "The present study shows that Cav-3 KO causes mild dilated cardiomyopathy and cellular hypertrophy without overt HF." (PMID 30028203, 2018).
Glucose intolerance (3 papers, 2015 to 2022). Glucose intolerance (GI) can be defined as dysglycemia that comprises both prediabetes and diabetes. "The goal of this study was to determine whether partial loss of CAV3 increases the susceptibility to lipid‐induced glucose intolerance and to define the underlying mechanisms." (PMID 27033451, 2016). "We found that lower expression levels of CAV3 accelerate the time of palmitate‐induced glucose intolerance by 50%, with mild changes of in vivo cardiac contractile function." (PMID 27033451, 2016).
Hypertension (3 papers, 2017 to 2024). The presence of chronic increased pressure in the systemic arterial system. "Mibefradil is a commercially available selective inhibitor of CaV3, originally approved for treatment of hypertension and angina pectoris." (PMID 33167547, 2020).
limb girdle muscular dystrophy type 1C (3 papers, 2021 to 2025). "RMD is often associated with limb-girdle muscular dystrophy type-1C, which is caused by mutations in the caveolin-3 (Cav3) gene." (PMID 41372236, 2025). "The possibility of a dystrophy was further substantiated by whole genome sequencing report of heterozygous mutation (Cys72Trp) in exon 2 of the CAV3 (+) gene which was pathogenic for limb girdle muscular dystrophy type 1C (LGMD1C)." (PMID 35611103, 2022). "Loss of function mutations in CAV3 have been described in limb-girdle muscular dystrophy type 1C and rippling muscle disease, an unusual disorder of hypercontraction." (PMID 34354129, 2021).
Anxiety (2 papers, 2021 to 2025). Intense feelings of nervousness, tension, or panic often arise in response to interpersonal stresses. "In contrast, a previous study showed that the Cav3.2KO mice spent less time in the open arms of the EPM and the center of the OFT, suggesting the Cav3.2KO mice exhibit anxiety-like behavior." (PMID 41067956, 2025). "We observed that Cav3.2KO mice displayed normal locomotor activity, olfactory function, and anxiety levels, but showed behavioral deficits in self-grooming, social novelty, novel object recognition, and contextual fear memory retrieval." (PMID 41067956, 2025). "In the OFT, the Cav3.2KO mice spent comparable time in the center zone relative to WT mice, indicating an anxiety-free phenotype." (PMID 41067956, 2025). "To determine whether the Cav3.2KO mice exhibited anxiety-like behavior, we utilized both the OFT and the elevated plus-maze (EPM)." (PMID 41067956, 2025). "Similarly, in the EPM, Cav3.2KO mice spent a comparable amount of time in the closed arms as WT mice, further supporting that the absence of anxiety-related phenotypes." (PMID 41067956, 2025).
Autosomal dominant limb-girdle muscular dystrophy (2 papers, 2011 to 2024). "Specifically, mutations in Cav3 that lead to an approximately 90% reduction in Cav3 protein levels are associated with autosomal dominant limb-girdle muscular dystrophy (LGMD1C)." (PMID 37848047, 2024). "In particular, mutations which lead to loss of the CAV3 protein, or a decrease of more than 90% of CAV3 expression, result in autosomal dominant limb-girdle muscular dystrophy (LGMD1C), manifesting by mild to moderate proximal muscle weakness." (PMID 21797990, 2011).
glioblastoma (2 papers, 2018 to 2020). The most malignant astrocytic tumor (WHO grade IV). "Previously, inhibition of CaV3 channels with mibefradil was reported to suppress the growth and stemness of glioblastoma stem-like cells and sensitise them to temozolomide chemotherapy." (PMID 33167547, 2020).
Hypercholesterolemia (2 papers, 2020 to 2022). An increased concentration of cholesterol in the blood. "Indeed, hypercholesterolemia and elevated TG have also been reported in LGMD type 1C (caveolin-3 mutations) and myotonic dystrophies types 1 and 2 (DMPK and CNBP mutations, respectively) — although often in the absence of control conditions or using experimental approaches." (PMID 36447272, 2022).
Hyperinsulinemia (2 papers, 2017 to 2020). An increased concentration of insulin in the blood. "Other analyses confirm that reductions in caveolin-3 inhibit insulin-stimulated glucose uptake in cardiac myoblasts and myocytes, and that hyperinsulinemia in cardiac myoblasts reduces caveolar levels of caveolin-3 and insulin-dependent phospho-Akt." (PMID 29202762, 2017).
lipodystrophy (2 papers, 2010 to 2013). A congenital or acquired disorder characterized by abnormal loss or redistribution of the adipose tissue in the body. "This gene was an attractive candidate because it had been shown to interact with caveolin-1, whose mutations cause lipodystrophy and with caveolin-3, whose mutations cause rippling muscle disease." (PMID 20300641, 2010). "Thus the multi-facetted symptoms of our patients combine the features seen in individuals with mutations in caveolin-1 (lipodystrophy) and in caveolin-3 (myopathy)." (PMID 20300641, 2010).
malignant melanoma (2 papers, 2015 to 2022). "Human melanoma cells express voltage-gated Ca2+ channels (VGCCs) from the families of the Cav1, Cav2, and Cav3 (T-type)." (PMID 35055084, 2022). "The Cav3 isoforms was reported to promote progression of melanoma cell cycle and blockade of T-type channels increased apoptosis in malignant melanoma." (PMID 35055084, 2022). "More importantly, mildly hypoxic conditions reminiscent of the hypoxic environment of skin and the high oxygen demand in metastasis increased CaV3 expression in melanoma, suggesting a role for CaV3 channels in proliferation of malignancies." (PMID 26010603, 2015). "It was observed that, CaV3 channels were selectively expressed in melanoma." (PMID 26010603, 2015).
mastitis (2 papers, 2024). Inflammation of breast tissue during lactation or postpartum due to an obstructed duct or infection. "Notably, the lncRNA-miRNA-mRNA ternary co-expression network of RHO, RCVRN, CSF1R, CAV3, and GATA4 genes is likely to be involved in the regulation of mastitis in Xinjiang brown cattle." (PMID 38674399, 2024). "The network analysis showed that the CSF1R, RHO, RCVRN, CAV3, and GATA4 genes were core nodes, suggesting that these genes could serve as candidate molecular markers for mastitis." (PMID 38674399, 2024).
muscle disorders (2 papers, 2019 to 2023).
Myocardial fibrosis (2 papers, 2019 to 2024). "Interestingly, CAV3 overexpression significantly alleviated cardiac dysfunction, and decreased the HW/TL, myocardium size and myocardial fibrosis in db/db mice." (PMID 38671439, 2024).
neuroblastoma (2 papers, 2013 to 2015). Neuroblastoma (NB) is the most common solid, extracranial childhood tumor. "To investigate whether T-type (CaV3) channels are substrates of Cdk5, we initially conducted whole-cell patch clamp recordings in the clonal neuroblastoma cell line N1E-115 which express prominent Ca2+ currents through CaV3 channels." (PMID 25760945, 2015).